INS (insulin)
Diseases named in the same sentence as INS in open-access papers (continued):
Sharing a sentence is not in itself a finding about the gene and the disease.
Insulin resistance (continued). "Although all of these have been associated with impaired insulin signalling and glucose metabolism, no single mechanism seems to explain how skeletal muscles with different metabolic characteristics develop insulin resistance under conditions of obesity." (PMID 34580412, 2021). "Cytokines also impair suppression of AT lipolysis, with resultant free fatty acid (FFA) release into the circulation, which hinders the ability of insulin to stimulate muscle glucose uptake and suppress hepatic glucose production, the two major factors in the pathogenesis of insulin resistance." (PMID 33717095, 2021). "However, our result showed a clear difference between males and females for insulin requirements, due to the higher insulin resistance seen in females, which would require different dosing protocols and/or a personalised approach." (PMID 33475909, 2021). "In the present analysis, we demonstrated that physical activity may influence bladder function and bladder expression of genes related to the insulin pathway in rats with obesity and insulin resistance." (PMID 33904660, 2021). "All these abnormalities in the adipose tissue and peripheral organs are critical for the development of the insulin resistance, and have widely been studied at molecular level in insulin-responsive tissues and organs (i.e., adipose tissue, skeletal muscle and liver)." (PMID 34208379, 2021). "Overall, the present investigation demonstrates that calystegines from Hyoscyamus albus provide cytoprotection to the HepG2 cells against insulin/glucose induced insulin resistance and apoptosis due to the regulation of SIRT1/Foxo1/G6PC/mTOR and NF-κB/JNK/TLR4 signaling pathways." (PMID 34034759, 2021). "Insulin resistance, or decreased insulin sensitivity (Si), is defined as the decreased responsiveness to the metabolic actions of insulin and the pathophysiological response to insulin-mediated glucose uptake in tissue." (PMID 34884295, 2021). "Decreased levels of insulin in the brain and central insulin resistance lead to impaired metabolism and functional activity of neurons, as well as to the changes in hypothalamic regulation of carbohydrate and lipid metabolism, food intake and endocrine functions." (PMID 34769198, 2021). "Serum FABP4 levels may result in insulin resistance, which in turn may lead to a compensatory increase in insulin secretion trying to maintain glucose homeostasis." (PMID 34174950, 2021). "It has been suggested that insulin resistance may impact several insulin-sensitive brain circuitries involved in eating behavior such as prefrontal regions." (PMID 34573180, 2021). "Although β-cells are competent in adapting to insulin resistance by secreting more insulin and increasing in mass to maintain glucose homeostasis, the high metabolic demand will eventually progress to β-cell exhaustion and a fraction of obese patients will develop diabetes." (PMID 33483593, 2021). "This increased oxidative stress may then enhance insulin resistance (possibly resulting from a reduced ability of the liver to extract insulin)." (PMID 34371987, 2021). "Indeed, our study showed that antisense oligonucleotides against AgRP reduced insulin resistance in the Evening group, suggesting that hypothalamic AgRP mediates evening feeding-induced impairment of muscular insulin sensitivity." (PMID 34639172, 2021). "As a further complication, insulin resistance reduces glucose delivery into the cardiomyocyte from insulin-sensitive GLUT4 (predominant route of glucose entry into cardiomyocyte) and GLUT8, forcing the heart to rely on the lower capacity (and insulin-independent) GLUT1 and SGLT1 routes." (PMID 33274396, 2021). "Obesity-induced insulin resistance results in a reduction in insulin-AKT phosphorylation." (PMID 34686659, 2021).
Insulin resistance (continued). "Additionally, the liver of HFD fed mice and the treated hepatocytes exhibited impairment of insulin-signaling and glycogen synthesis, revealing miR-96 as a promoter of hepatic insulin resistance pathogenesis in obese states (Hepatocyte)." (PMID 34072137, 2021). "Consistently, these different mtDNA backgrounds altered aspects of glucose metabolism on the C57BL/6J nDNA background, including exogenous glucose and insulin sensitivity, as well as insulin sensitivity defined by the modified Homeostatic Model Assessment of Insulin Resistance (mHOMA-IR)." (PMID 34370595, 2021). "Indeed, exercise has been largely demonstrated to improve the peripheral insulin sensitivity in T2D patients and to have a beneficial effect on insulin resistance." (PMID 33844166, 2021). "As currently described in the literature, our experimental model of diet‐induced obesity led to systemic insulin resistance with increased levels of fasting blood glucose and insulin, and a systemic altered response to insulin compared to mice fed with low‐fat diet." (PMID 33682327, 2021). "Furthermore, diminished hypothalamic insulin signaling results in a rapid onset of hyperphagia and increased fat mass sufficient to promote obesity and induce peripheral insulin resistance." (PMID 33927690, 2021). "Physical exercise, which directly protects muscle glucose metabolism and attenuates insulin resistance, may restore the impaired insulin secretory capacity and rebuild glycemic control." (PMID 35392577, 2021). "Consequently, insulin signaling is impaired and insulin resistance occurs, which would also be compensated for by increased insulin secretion." (PMID 34373742, 2021). "Further, the onset of DM and IGT is characterized by insulin resistance, hyperinsulinemia, insulin stimulation of IGF-I production in the liver through the upregulated GH signaling pathway (e.g., upregulated expression of the hepatic GH receptor), and decreased IGFBP-1 level." (PMID 34239560, 2021). "To assess whether short-term TGR5 activation improves insulin resistance in muscle cells, we evaluated insulin-induced Akt phosphorylation of TGR5-expressing C2C12 myotubes that developed insulin resistance by palmitate." (PMID 33262218, 2021). "Adipose insulin resistance may develop before other metabolic alterations and directly contribute to impaired insulin action in skeletal muscle and liver." (PMID 34321614, 2021). "Notably, our data demonstrated that pancreatic β cell‐derived mutant miR‐29a inhibits hepatic insulin signalling, promoting insulin resistance." (PMID 33520119, 2021). "T2D is developed by a mixture of insulin resistance and impaired secretion of insulin." (PMID 34889890, 2021). "Moreover, SGLT-2 inhibitors therapy improves insulin sensitivity and ameliorates insulin resistance." (PMID 33598483, 2021). "This is in accordance with the hypothesis that idiopathic hyperglycemia of the preterm neonate is related to both insulinopenia (due to abnormality in insulin biosynthesis during post-translational stages with pro-insulin accumulation) and insulin resistance." (PMID 34447729, 2021). "Quercetin may exert antidiabetic effects through various mechanisms, including promoting insulin secretion, improving insulin resistance, maintaining glucose homeostasis, and inhibiting inflammation, oxidative stress, and apoptosis." (PMID 34257817, 2021). "Metabolomic measures are differentially insulin sensitive and may thus be differentially affected by the development of insulin resistance." (PMID 34106350, 2021). "Furthermore, several studies have demonstrated that interventions or treatments with exogenous insulin alleviated dementia symptoms in patients with insulin resistance and improved their Mini-Mental State Examination (MMSE) scores." (PMID 34577866, 2021). "Glucocorticoids may induce post-receptor insulin signaling defects, also contributing to insulin resistance." (PMID 33800138, 2021).
Insulin resistance (continued). "About 90–95% of these patients have type 2 DM, which is characterized by progressive reduction of insulin secretion with or without insulin resistance and is a major risk factor for renal and cardiovascular diseases." (PMID 33945582, 2021). "Consistent with the results of these studies, we found decreased calcitriol levels in patients with GDM in early pregnancy, which may be related to insulin resistance and impaired insulin secretion during pregnancy, subsequently increasing the risk of GDM." (PMID 33628838, 2021). "Further weight gain following an increased insulin dosage would aggravate insulin resistance." (PMID 34852815, 2021). "Moreover, spontaneous lipolysis was positively associated with Insulin resistance parameter derived from IVGTT (r = 0.50, p = 0.002), fasting plasma insulin levels (r = 0.40, p = 0.02) and HOMA-IR (r = 0.46, p = 0.006)." (PMID 33574418, 2021). "Indices of insulin resistance (glycated hemoglobin, insulin, and insulin resistance) and lipids (triglycerides, total cholesterol, and high-density lipoprotein cholesterol [HDL-C]: total cholesterol ratio) improved in the ginger group compared to the placebo group." (PMID 34239993, 2021). "Furthermore, HRT decreased low-density lipoprotein cholesterol, total cholesterol, fasting insulin, fasting plasma glucose and homeostasis model assessment of insulin resistance in both peri- and postmenopausal controls, compared with baseline." (PMID 34130678, 2021). "Skeletal muscle is considered an important insulin-responsive endocrine organ, and decreased muscle mass contributes to impaired glycemic control and insulin resistance, which could contribute to the development of atherogenic dyslipidemia." (PMID 34436238, 2021). "PCOS women in their second trimester of pregnancy were insulin resistant accordingly to their homeostatic model assessment for insulin resistance (HOMA-IR), and had on average 339.3 gram lighter babies compared to gestational-age and weight matched healthy controls on delivery (p<0.05)." (PMID 34211435, 2021). "Though glycemia is the most important predictor of outcomes, the degree of insulin resistance associated with obesity and type 1 diabetes is also important in predicting future complications, and this is not addressed by insulin titration alone." (PMID 33828529, 2021). "Curcumin has various effects on insulin levels and insulin resistance in women with PCOS." (PMID 34579002, 2021). "However, in recent studies, insulin-induced vasodilation was confirmed to be impaired in insulin-resistant patients, and patients with obesity or insulin resistance have elevated ET-1 concentrations in the blood." (PMID 33967958, 2021). "Additionally, in the Paleo group, an improvement in insulin sensitivity was noted in patients with the highest insulin resistance." (PMID 33801152, 2021). "Indeed, GRK2 expression is increased in key tissues in different experimental models of insulin resistance, and its downregulation ameliorates the alterations of glucose homeostasis and insulin signaling in response to different insults." (PMID 33467677, 2021). "For example, TNF-α can ultimately lead to insulin resistance, reducing insulin sensitivity." (PMID 34836432, 2021). "Moreover, whereas fasting blood glucose was slightly but significantly decreased with HFD (−7.8%), insulin concentration was higher (+56.3%), which drifted into an insulin resistance, as it showed the increase of HOMA-IR index (+72.6%)." (PMID 34943104, 2021). "We hypothesize that Chi3L1 gene expression is important in the development of hepatic insulin resistance characterized by the generation of pAKT, pGSK, and pERK in wild type and Chi3L1 knockout (KO) murine liver following insulin stimulation." (PMID 33498326, 2021). "Also, to evaluate the effects of these drugs on insulin resistance, we performed insulin tolerance test (ITT)." (PMID 34373487, 2021).
Insulin resistance (continued). "In particular, the TyG index that integrates serum fasting concentrations of triglycerides and glucose, has been broadly utilized as a substitute index for exploring resistance to insulin instead of Homeostatic Model Assessment for Insulin Resistance (HOMA-IR) in the medical settings." (PMID 34742318, 2021). "Therefore, resistance-inducing factors can act on the insulin signaling on both myocytes and endothelial cells to induce insulin resistance." (PMID 34075130, 2021). "High SUA levels may inhibit nitric oxide bioavailability and since insulin requires nitric oxide to stimulate glucose uptake high SUA may induce insulin resistance." (PMID 35059366, 2021). "Leucine is associated with insulin resistance and a higher risk of T2DM, however, studies have also shown improved insulin sensitivity with leucine supplementation in vivo." (PMID 33400857, 2021). "However, 9 weeks of probiotic supplementation elicited significant differences in both serum insulin (+ 1.2 ± 1.2 vs. +5.0 ± 1.1 μIU/mL, probiotic vs. placebo, p = 0.02) and insulin resistance (−0.2 ± 0.3 vs. +0.7 ± 0.2 μIU/mL, p = 0.01) from the baseline." (PMID 33450885, 2021). "Increased TNF-α concentrations might induce insulin resistance via changes in the adipocyte insulin signaling pathway, as suggested in one study." (PMID 33954196, 2021). "Indeed, miR-149-5p was upregulated in the liver of HFD-induced hepatic insulin resistance mice, and miR-375 is highly expressed in pancreatic islets involved in insulin secretion and glucose homeostasis." (PMID 34850865, 2021). "Intra-myocardial toxic metabolites of FAs metabolism and triacylglycerol, such as diacylglycerol, ceramides and acylcarnitines, are responsible for severe insulin resistance by interrupting insulin signal cascade at different levels and multiple steps of glucose metabolism." (PMID 34899326, 2021). "This, together with the increasing levels of insulin and glucose, could be interpreted as the minipigs evolving towards a state of chronic obesity with signs of insulin resistance." (PMID 34066330, 2021). "On the other hand, glucose transporter 4 (GLUT4), which is coded by the SLC2A4 gene, is the center of most studies on insulin resistance, since it is the major means of glucose transport in insulin-sensitive peripheral tissues (i.e., skeletal muscles and adipose tissues)." (PMID 34360895, 2021). "Additionally, the association of the parameter values with frequently used measures of insulin secretion and insulin resistance were evaluated to assess model structure." (PMID 33788828, 2021). "Moreover, previous studies have revealed that supplementation of vitamin D in people with prediabetes or insulin resistance and inadequate vitamin D levels improves insulin sensitivity." (PMID 34371843, 2021). "Given the knowledge that insulin resistance may be a contributing factor to worsening cardiac function, there is interest in using medications that can improve insulin sensitivity, glucose homeostasis and in turn possibly also have beneficial cardiac effects." (PMID 34778146, 2021). "In order to investigate whether increased adiponectin levels after tocilizumab administration positively affect insulin sensitivity, the homeostatic model assessment of insulin resistance (HOMA-IR) was assessed." (PMID 33572989, 2021). "In addition, it was confirmed that berberine acted via AMPK regulation of the insulin gene promoter in mice, and it was found that insulin resistance and glucose tolerance were improved." (PMID 34836306, 2021). "The DKI mutation used to disrupt whole-body AMPK-glycogen binding in mice leads to simultaneous increases in serum insulin levels and adiposity, contributing to the progression of glucose intolerance characteristic of the early stages in the development of insulin resistance." (PMID 34502525, 2021).
Insulin resistance (continued). "Consistent with HFD increasing iNOS levels in the DVC, we demonstrated that mitochondrial fission increases iNOS levels in the DVC and that a reduction of iNOS levels can protect against the development of HFD-dependent insulin resistance and restore insulin sensitivity in an obese model." (PMID 33227495, 2021). "The increased plasma insulin AUC after an IAGTT suggests insulin resistance in comparison to the values obtained for lean pigs, although the concentration of glucose remained low which could indicate the absence of a peripheral insulin resistance." (PMID 33854837, 2021). "Inflammatory factors can influence the transmission of the insulin signaling pathway downstream by different pathways to induce the phosphorylation of insulin receptor substrates at serine residues, which can reduce the physiological function of insulin and result in insulin resistance." (PMID 34966805, 2021). "Furthermore, prior studies have shown that these deleterious lipid intermediates have the greatest impact on the development of skeletal muscle insulin resistance, which is responsible for 70–80% of whole-body insulin-stimulated glucose uptake." (PMID 34445300, 2021). "Interestingly, the male antibiotic groups (ABT, ABT + PRE) had increased leptin levels compared to CTR at the end of the study, however, fasting insulin levels as well as insulin resistance was strictly increased in the ABT group." (PMID 33445530, 2021). "Stimulation with 100 nM insulin induced a dramatic increase in glucose uptake in control adipocytes, but glucose uptake was significantly impaired in high serum treated cells, indicating that this method induced insulin resistance in 3T3L1 adipocytes." (PMID 33498179, 2021). "Insulin resistance is considered to be an adverse metabolic and a key risk factor for developing cardiovascular diseases, and insulin receptor substrates (IRS) are key modulators of insulin signal transduction pathways in the heart." (PMID 33668039, 2021). "It is well-known that insulin resistance and impaired insulin signalling may be a contributory factor to the progression of type 2 diabetes." (PMID 34748564, 2021). "In addition, BMPER levels negatively correlated with body weight and plasma levels of insulin and TGs, suggesting an association between decreased BMPER levels and conventional serum markers of insulin resistance." (PMID 33772019, 2021). "Sphingolipid signaling pathway: there is some evidence that intracellular lipids may contribute to insulin resistance by inhibiting insulin signaling, and the intracellular lipid pools are related to the sphingomyelin signaling pathway." (PMID 34306142, 2021). "Results revealed that Zataria multiflora could significantly reduce insulin resistance, insulin serum level, and blood pressure compared to the placebo group." (PMID 34426744, 2021). "In addition, SGLT2 inhibitors have been shown to reduce insulin resistance and ameliorate peripheral insulin sensitivity." (PMID 34439553, 2021). "Despite normal body weight, Off-HFD mice developed insulin resistance with defects in hepatic insulin action and insulin-stimulated glucose uptake in skeletal muscle and brown fat, and these metabolic effects were associated with hepatic inflammation in Off-HFD mice." (PMID 33769706, 2021). "Furthermore, many are overweight or obese, due primarily to insulin compensation resulting from insulin resistance." (PMID 34070103, 2021). "Hence, we used the interplay of glucose and insulin levels by the HOMA-IR index to estimate insulin resistance, which remains a crude estimate." (PMID 33688395, 2021). "For example in prostate cancer, insulin resistance and changes in body composition are side effects of androgen deprivation therapy, and aerobic training has been shown to increase peripheral tissue insulin sensitivity and elevate muscle protein content of GLUT4." (PMID 33801684, 2021).